ATM (ATM serine/threonine kinase)
Diseases named in the same sentence as ATM in open-access papers (continued):
Sharing a sentence is not in itself a finding about the gene and the disease.
tumor (continued). "With a focus on clinically actionable alterations, all IDH1 and ATM mutations were consistent in both tumor and liquid biopsies." (PMID 39273408, 2024). "We believe that this prolonged PFS is likely due to enhanced sensitivity of the tumor to radiation therapy due to ATM loss as well as augmented activity from the PARP inhibitor and IO therapy." (PMID 39156348, 2024). "Mechanistically, the treatment of drugs induces DNA double-strand breaks in tumor cells, causing the activation of ATM and ATR." (PMID 39045048, 2024). "We found that homozygous loss of ATM caused a marked increase in the in vitro and in vivo sensitivity of tumor cells to niraparib, which is consistent with previous findings." (PMID 38807759, 2024). "Among all samples assayed via molecular testing (n = 260), ATM variants were detected in 15 of 159 circulating tumor cell DNA samples (9%), versus in 21 of 101 solid tumor biopsies (21%) (P = .010)." (PMID 38260227, 2024). "Niraparib monotherapy treatment caused significant tumor growth inhibition (>90% TGI) in two out of six PDX models with ATM biallelic mutations." (PMID 38807759, 2024). "Increased MICA/B expression in tumor is regulated by the activation of the DNA damage response (DDR) initiated by ATM (ataxia telangiectasia, mutated) or ATR (ATM‐ and Rad3‐related) protein kinases." (PMID 38882209, 2024). "ATM alterations are associated with a poor prognosis; germline mutations are linked to higher tumor grades and lethal PCa." (PMID 38339274, 2024). "Alterations in DNA damage sensor genes were also prevalent across tumour types, with ATM mutations found in ~5% of BC, NSCLC, CRC and PC specimens." (PMID 37821580, 2023). "The Ataxia Telangiectasia Mutated (ATM) gene, also known as ATM serine/threonine kinase, is a crucial tumor suppressor gene that belongs to the phosphatidylinositol 3-kinase-related protein kinase (PIKK) superfamily." (PMID 37951143, 2023). "The ataxia-telangiectasia-mutated (ATM) gene, which has an essential role in controlling and regulating the cellular cycle, is also a tumor suppressor that can phosphorylate LKB1 as a response to metformin." (PMID 37491250, 2023). "Clinical benefit was greatest amongst patients with BRCA2 and ATM mutations, including durable objective tumour responses, with minimal toxicities attributable to combining olaparib with durvalumab." (PMID 37365284, 2023). "Other than CHK1, the complete loss of the ATM/CHK2 axis is considered tumor‐promoting and the ATM locus is frequently affected by deletions of the long arm of chromosome 11." (PMID 37485814, 2023). "On the other hand, when ATM variants were compared according to tumor localization, left BC was numerically more frequent in the LP group, but it was not statistically significant." (PMID 38021491, 2023). "As it is known that ATM is associated with the degradation of TOP2β, and induces tumor cells to exhibit resistance to VP-16." (PMID 36650267, 2023). "Intriguingly, 11q heterozygous deletions and ATM hemizygous mutations are mutually exclusive in NB tumours." (PMID 37020276, 2023). "Whole-exome sequencing (WES), immunohistochemistry (IHC), and Western blotting (WB) were used to characterise the baseline ATM status across a panel of ATM mutated patient-derived xenograft (PDX) models from a range of tumour types." (PMID 37627223, 2023).
tumor (continued). "Integration of genetic alterations (SWI/SNF complex mutations, ATM mutations and chr8q CNAs) improved the performance of a nomogram based on tumour stage and residual disease (concordance index 0.75 vs. 0.70, p < .05)." (PMID 37272300, 2023). "From this perspective, the ATM/CHK2/WEE1 pathway inhibitors cause the increased expression of PD-L1 in tumor cells and promote immune escape, so they are more suitable for the combined application of PD-1/PD-L1 inhibitors." (PMID 37109350, 2023). "del(11q), involving the ATM gene, a tumor suppressor involved in recognizing DNA damage, is found deleted in 10–20% of cases (where a minor proportion (20-25%) of these also carry a second ATM mutation) while trisomy 12 is detected in 10-15% of cases." (PMID 37035166, 2023). "In GBM, miR-223-3p functions as a tumor-suppressor miRNA; its overexpression enhances radio-/chemosensitivity in cell culture models as miR-223-3p targets ataxia telangiectasia mutated (ATM)." (PMID 36831894, 2023). "The ATM c.1236-2A>T mutation was also identified in 33% (5/15) of primary tumor samples but in only 9% (1/11) of metastatic samples." (PMID 38098507, 2023). "Somatic ATM mutations also occur in several sporadic tumor types, especially in hematologic malignancies." (PMID 36672401, 2023). "DNA damage-induced ataxia telangiectasia mutated (ATM) kinase activated by radiotherapy transcriptionally inhibits the expression of SLC7A11 to promote tumor ferroptosis." (PMID 37714846, 2023). "ATM/ATR-mutated patients had significantly higher tumor mutational burdens (TMB; P < 0.001) and microsatellite instabilities (MSI; P = 0.023), but not chromosomal instabilities, than those without any ATM/ATR variations." (PMID 38041093, 2023). "Tumor cells with a loss of DDR function or defects in the ataxia telangiectasia mutated (ATM) gene are generally more dependent on ATR for survival, suggesting that ATR is an attractive anticancer drug target based on its synthetic lethality." (PMID 37298997, 2023). "Although tumor localizations were similar in all ATM variant groups, it was slightly more localized in the left breast in the LP group." (PMID 38021491, 2023). "In the in vitro assay, ZH-12 showed more potent antiproliferative activity in ATM-deficient tumor cells than in ATM-normal tumor cells." (PMID 37298997, 2023). "ATM is a master regulator of DNA damage response, and altered ATM expression or function has been reported to be associated with PARPi sensitivity in several tumor contexts." (PMID 36307400, 2022). "The underlying mechanisms by which ATM activity promotes tumor progression are only partly elucidated." (PMID 35804995, 2022). "Mouse xenograft studies have shown that the DNA-PK inhibitor AZD7648 can enhance the efficacy of olaparib, a PARP1/2 inhibitor, in FaDu ATM knockout (KO) tumour models, since the loss of ATM has been shown to sensitise cells to DNA-PK inhibitor treatment." (PMID 35617197, 2022). "In patients, tumors with mutations or low expression of both ARID1A and ATM/CHK2 exhibit increased tumor-infiltrating lymphocytes and are associated with longer patient survival." (PMID 35572596, 2022). "Taken together, these results confirm that ATM loss confers sensitivity to PARPi in cell lines from a range of different tumor types." (PMID 36969741, 2022). "Our data indicate that mRNA expression of ATM/ERBB2 was significantly associated with tumour grade (p = 0.011), disease stage (p = 0.009) and tumour shape (p = 0.001)." (PMID 36056635, 2022).
tumor (continued). "Instead, we identified a pathogenic mutation in all AEC tumor regions analyzed which affected a splice site of the Ataxia Telangiectasia Mutated gene (ATM, c.6096-1 G > A) and was associated with loss-of-heterozygosity (LOH)." (PMID 35145232, 2022). "Some literature stated that tumor cells with ATM deficiency were more sensitive to Olaparib, which prevented DNA double strands from repairing and elicited damage accumulation, leading to cell apoptosis ultimately." (PMID 35910852, 2022). "We have shown that initiation of ATM‐associated DDR is the cause for tumor cell senescence induced by citrate." (PMID 34747157, 2022). "Yet, they had higher tumor mutation burden, and higher frequency of ATM and BRCA1 mutations (44% vs. 10%, p = 0.002 and 21% vs. 4%, p = 0.018, respectively)." (PMID 36362213, 2022). "The PARP inhibitor Olaparib has a good response rate in patients with ATM mutations and it significantly controlled tumor growth in the AEC PDX models." (PMID 35145232, 2022). "They showed that defects in BRCA2 and ATM were strongly associated with poor time to progression independently of clinical prognostic factors and circulating tumor DNA abundance (p < 0.001)." (PMID 35448200, 2022). "The same group found that ATM expression levels negatively correlate with type 1 IFN gene expression in human tumor tissues and that patients with tumors harboring ATM mutations have a favorable response to ICI." (PMID 36276148, 2022). "In tumor cells, ataxia–telangiectasia mutated (ATM) and ATM- and Rad3 Related (ATR) are major members of DNA damage checkpoints and are activated by different types of DNA damage." (PMID 35053488, 2022). "BRCA1/2 and ATM are tumor suppressors that are commonly mutated or dysregulated in breast or ovarian cancers." (PMID 36254250, 2022). "The expression of HER2/ATM was significantly associated with tumour grade, disease stage, tumour shape, lymph node and metastasis." (PMID 36056635, 2022). "Co-administration of elimusertib (50 mg/kg) and olaparib (30 mg/kg) in an ATM loss patient-derived prostate cancer model resulted in better tumor growth inhibition and longer survival of animals." (PMID 35458687, 2022). "Examples of such tumor-specific alterations include ATM loss, Cyclin E1 (CCNE1) amplification, and APOBEC3 expression." (PMID 35458687, 2022). "The immunohistochemical analysis of tumour samples showed increased yH2AX and ATM expression was associated with response, as well as increased expression of the mismatch repair proteins MLH1 & MSH6." (PMID 34256782, 2021). "On the other hand, the ATM-mutated HCT116 tumor xenografts were significantly reduced by the combination compared to niraparib or irinotecan monotherapy." (PMID 33407715, 2021). "In this trial, an objective radiological response was observed in three solid tumor patients with ATM loss (defined as observing ATM staining in less than 1% of tumor cell nuclei)." (PMID 34885025, 2021). "Consistently, somatic mutations of ATM were observed in hematologic malignancies at higher frequencies than in other types of tumor." (PMID 34069817, 2021). "The pathogenic germline variants in mCRPC, recurrent germline and somatic variants, and hotspot positions in different tumour types were mapped onto ATM, BRCA1, BRCA2, and MUTYH available structures, in order to find 3D-clusters of variants." (PMID 34253785, 2021).
tumor (continued). "In IC-006 model, derived from a tumor bearing an ATM mutation, the combination is effective at two dose levels (1:0.01 and 0.5–0.005), while in IC-011 it is only effective at the higher dose level (1:0.01)." (PMID 33407715, 2021). "Somatic mutations in ATM occur in many tumor types, particularly hematologic malignancies, and generally have been associated with inferior prognosis." (PMID 34174931, 2021). "PARP-inhibitors have shown promising results in tumor cells defective in DNA damage repair, in particular DSBs, as ATM-mutated tumor cells." (PMID 34068084, 2021). "In this trial, ATM deficiency was defined immunohistochemically as observing ATM staining in less than 25% of tumor cell nuclei." (PMID 34885025, 2021). "TAK1 is also activated by TRAF6 through ataxia-telangiectasia mutated (ATM) in DNA-damaged tumor cells." (PMID 33966040, 2021). "Non-sense variant p.E1996* and missense variant p.A1014D in tumor suppressor ATM are predicted as driver mutations according to OncodriveMUT, whereas alterations in gene ZFHX4 are predicted to be a passenger mutation." (PMID 34136393, 2021). "Considering the most representative variants shared by tumor fragments and plasma of dogs, we identified important gene variations in ATM (C > A mutation), CCNE1 (G > C), FGFR4 (C > T), and GATA3 (G > A and C > CT)." (PMID 34680380, 2021). "A retrospective review of his tumor biopsy revealed a Gleason score 9 (5 + 4) adenocarcinoma in 12/12 cores with ATM (G494D) somatic mutation." (PMID 34839812, 2021). "RT-induced DSBs and subsequent ATM/ATR/CHK1 kinase activities have also been implicated in upregulation of tumor PD-L1 expression through direct STAT1/3-IRF1 activation, independent of neoantigen production." (PMID 34631532, 2021). "ATM mutation was significantly associated with higher tumor stage (p = 0.012) and shorter overall survival (OS) (p = 0.041)." (PMID 33854094, 2021). "As a combination therapy, AZD6738 augments carboplatin, bendamustine, and cyclophosphamide effects and reduces the tumor burden in an ATM-deficient DLBCL mouse model." (PMID 34732266, 2021). "This indicates that the level of ROS caused by anti-tumor drugs is increased, which initiates the ATM activation mechanism and induces cell senescence." (PMID 34421351, 2021). "Ataxia–telangiectasia mutated (ATM) is a regulator of many developmental processes within tumor cells including migration, metabolic regulation, cell cycle checkpoint regulation, and DNA double‐strand break repair." (PMID 33742560, 2021). "Ataxia telangiectasia mutated (ATM) protein is an important factor affecting the radiosensitivity of tumor cells." (PMID 34055781, 2021). "In our study the ATM gene was mutated in almost samples from all patients, suggesting that loss of gene function is a founder event during tumor progression." (PMID 34853661, 2021). "GADD45A is associated with DNA damage and is proapoptotic, and ATM, as a tumor suppressor gene, plays a role in the initiation and/or progression of MCL." (PMID 34174847, 2021). "ATM functions in early stage of cell signal transduction, and ATM deficient cells show abnormal cell cycle and tumor susceptibility." (PMID 32518522, 2020). "ATM-mutated tumours demonstrate varying reductions in ATM expression and signalling, compared with total loss in KO models." (PMID 32444694, 2020). "In the present study, we report for the first time that F-HN co-expression and NDV infection trigger ataxia telangiectasia-mutated (ATM)-dependent DSB lesions in tumor cells to promote viral replication and syncytium formation, respectively." (PMID 32479542, 2020). "They found that 8% of PDAC tumor samples had somatic ATM alterations, either mutations, LOH, or both." (PMID 31963441, 2020). "Dual caspase-2/ATM deficiency increased the incidence of tumor formation from 31% in control Atm-deficient mice to nearly 64% in Casp2/Atm double knockout mice." (PMID 33425918, 2020).
tumor (continued). "Matched tumor/normal NGS identified a germline pathogenic ATM mutation with copy number gain in the tumor." (PMID 31963394, 2020). "Four variants showed LOH in the tumor specimen (ATM c.4709T>C; CHEK2 c.1036C>T; PALB2 c.1001A>G, and RAD50 c.281T>C), which is an indication of pathogenicity." (PMID 33134171, 2020). "Combination activity caused tumour regressions only in the ATM-deficient CTG-0828 model, with near-total loss of protein expression." (PMID 32444694, 2020). "Some studies also looked at loss of total ATM protein by immunohistochemistry (IHC), which varies from 5 to 41% across different tumor types." (PMID 33224881, 2020). "PTEN-deficient in vitro cell and in vivo tumour models were shown to be selectively sensitised to treatment with ATM inhibitors." (PMID 33396656, 2020). "Despite observing combination activity in both ATM-deficient in vivo models, tumour regressions were only observed in the CTG-0828 PDX." (PMID 32444694, 2020). "Four variants of uncertain significance showed loss of heterozygosity in the tumor (ATM c.4709T>C; CHEK2 c.1036C>T; PALB2 c.1001A>G, and RAD50 c.281T>C), which is an indication of pathogenicity." (PMID 33134171, 2020). "Of genes previously reported as commonly mutated in PNETs, only PDGFRA and MTOR were found to be mutated in a few tumor samples, and other genes, including ATM, ATRX, TSC2, DAXX, VHL, and MEN1, were mutated only in individual samples." (PMID 32586046, 2020). "TCGA network has observed similar retention of a wild-type ATM allele in the tumor of a patient with a pathogenic germline ATM variant." (PMID 31963441, 2020). "Together, these data demonstrate the potential therapeutic advantage of combining olaparib and AZD6738 in ATM-deficient tumours." (PMID 32444694, 2020). "Conversely, patients with EGFR mutations where characterized by lower CD3 T lymphocytes infiltrating and surrounding tumor cells, while mutations in the ATM gene were associated with the high immune risk profile." (PMID 32646072, 2020). "An ATM variant, p.R1466*, was also detected only in tumour #2, and the variant allele frequency was 3%." (PMID 31929516, 2020). "Together the in vitro and in vivo data demonstrate pre-clinical synergy between olaparib and AZD6738 in ATM-deficient tumours and provide a mechanistic rationale for clinically targeting tumours with ATM-inactivating mutations across multiple tissue types." (PMID 32444694, 2020). "Roberts and colleagues identified somatic LOH of the ATM locus in the tumor of a patient with a pathogenic germline ATM variant." (PMID 31963441, 2020). "RETAIN is a Phase II study that enrolls patients with MIBC to undergo surgery or a bladder-preserving approach according to the mutational profile of the tumor (including ATM, RB1, FANCC and ERCC2 mutations) (NCT02710734)." (PMID 33266377, 2020). "Here, we discuss the potential for extending PARP inhibitor therapies to tumours with deficiencies in the DNA damage-activated protein kinase, Ataxia-Telangiectasia Mutated (ATM)." (PMID 32183301, 2020). "Our IHC results suggest that ATM c.3806A > G is associated with tumor development in the index patient." (PMID 31811167, 2019).